TLR2 (toll like receptor 2)
Diseases named in the same sentence as TLR2 in open-access papers (continued):
Sharing a sentence is not in itself a finding about the gene and the disease.
diaphragmatic hernia (1 paper, 2024). A congenital or acquired weakness or opening in the diaphragm which allows abdominal contents to protrude into the chest cavity; congenital diaphragmatic hernias are caused when the embryonic diaphragm fails to fuse. "We found that administering a single dose of atypical TLR2/4 ligands (CS1 or CS2), 3 days after nitrofen, cured diaphragmatic hernia in 73% of the fetuses and repaired the lesion with complete diaphragm closure being on the other hand nontoxic for the mothers or pups." (PMID 39425191, 2024).
Dyskinesia (1 paper, 2024). A movement disorder which consists of effects including diminished voluntary movements and the presence of involuntary movements. "In vivo, apart from dyskinesia, MPTP mice exhibited constipation, urinary dysfunction, and cardiovascular failure, which were associated with the deposition of p-α-syn in vagus nerve SCs, TLR2 activation, and vagus nerve demyelination." (PMID 38278799, 2024).
dyslipidaemia (1 paper, 2019). "It should be acknowledged that TLR2 and TLR4 stimulants are well-established to trigger systemic inflammation and dyslipidaemia when delivered at high doses intravenously." (PMID 31316501, 2019).
Dysmenorrhea (1 paper, 2017). Pain during menstruation that interferes with daily activities. "After statistical analysis confirmed that: The gene expression of TLRS (TLRS = TLR1 + TLR2 + TLR3 + TLR4 + TLR5 + TLR6 + TLR7 + TLR8 + TLR9) in severe and moderate dysmenorrhea group was significantly higher than that in minimal dysmenorrhea group in EU and EC (P < 0.05 or P < 0.01)." (PMID 28779087, 2017).
dyspepsia (1 paper, 2013). An uncomfortable, often painful feeling in the stomach, resulting from impaired digestion. "A case-control study comprising 284 ethnic Chinese individuals (70 non-cardia GC cases and 214 functional dyspepsia controls) was conducted for the genotyping of TLR2 -196 to -174del, CD14 -260 C/T and TLR4 rs11536889 using PCR, RT-PCR and mass spectrometry." (PMID 23565226, 2013).
Epiretinal membrane (1 paper, 2024). An epiretinal membrane is a thin sheet of fibrous tissue on the surface of the retina along the inner limiting membrane. "The aim of this study was to confirm the expression of TLR2 and TLR4 in the fibrocellular membranes and vitreal fluids (soluble TLRs) of patients suffering of epiretinal membranes (ERMs) and assess their association with disease severity, complement fragments and inflammatory profiles." (PMID 39062973, 2024).
familial Mediterranean fever (1 paper, 2020). Familial Mediterranean fever (FMF) is an autoinflammatory disorder characterized by recurrent short episodes of fever and serositis resulting in pain in the abdomen, chest, joints and muscles. "Similar findings have been described in patients with familial Mediterranean fever, in whom increased expression of TLR2 in monocytes has been demonstrated, even during quiescent disease." (PMID 32164729, 2020).
fertility disorders (1 paper, 2025). "Although not the focus of this review, higher Toll-like receptor 2 expression on cervical monocytes has been observed in seropositive women, indicating previous CT infection, who already experienced fertility disorders." (PMID 41031366, 2025).
gallstones (1 paper, 2025). Solid crystalline precipitates in the biliary tract, usually formed in the gallbladder, resulting in the condition of cholelithiasis. "We then established a gallstone mouse model by gavaging C. scindens and subsequently used Robinin to inhibit TLR2 and Reparixin to inhibit CXCL1." (PMID 40309357, 2025).
gestational diabetes (1 paper, 2016). Carbohydrate intolerance first diagnosed during pregnancy. "Interestingly, TLR2 was found to be upregulated in women who exhibited normal glucose tolerance but later developed gestational diabetes when compared to the women who remained normoglycemic." (PMID 28536605, 2016).
gnathostomiasis (1 paper, 2023). "Similarly, our present findings revealed TLR2 downregulation, which may explain the defect in innate immunity in gnathostomiasis." (PMID 37600806, 2023).
hearing loss (1 paper, 2020). "Results obtained in patients with sudden sensorineural hearing loss revealed that those with the most severe hearing loss had the highest Tlr2 expression." (PMID 33192313, 2020).
hemorrhage (1 paper, 2019). Loss of blood from the vascular compartment to the exterior or into nonvascular body space as a result of rupture or severance of the blood vessels. "MetHb is an endogenous ligand of toll-like receptor 2 (TLR2) and toll-like receptor 4 (TLR4) that induces pro-inflammatory cytokine and tumor necrosis factor α (TNF-α) production after hemorrhage." (PMID 31357546, 2019).
hemorrhagic stroke (1 paper, 2021). A stroke caused by a bleed on the brain. "Antibodies can provide a more specific means of inhibiting TLR2 and 4; indeed, MTS510, a monoclonal antibody, has already been used to inhibit TLR4 expression in ischemic and hemorrhagic stroke in preclinical models." (PMID 34576137, 2021).
hereditary cancer syndromes (1 paper, 2021). "Among them, APC, FAT4, CTNND1 and TLR2 seem to be the most promising genes because of their role in hereditary cancer syndromes, tumor suppression, cell adhesion and Helicobacter pylori recognition, respectively." (PMID 33525650, 2021).
hookworm infection (1 paper, 2008). "As for TLR2, low expression of SOCS-3 was associated with S. haematobium rather than hookworm infection." (PMID 18414649, 2008).
hydatidosis (1 paper, 2023). "Based on recent studies, the potential role of TLR2/TL4 polymorphism has been presented as a predisposing factor in patients with recurrent hydatidosis (RH)." (PMID 37796859, 2023).
hydronephrosis (1 paper, 2009). Collection of urine in the renal pelvis that results in dilatation of the renal pelvis and calyces. "Therefore, we wondered if tubulo-interstitial damage that developed upon obstructive hydronephrosis may be associated with TLR2 expression." (PMID 19479087, 2009).
Hyperinsulinemia (1 paper, 2019). An increased concentration of insulin in the blood. "Further, an increase of expression (MFI) of TLR2, a well-characterized immune scavenger receptor, on monocytes was observed in response to hyperinsulinemia." (PMID 30983877, 2019).
insomnia (1 paper, 2017). A sleep disorder characterized by difficulty in falling asleep and/or remaining asleep. "Our data suggest that interventions to block Tlr2 signaling may be novel and promising avenues for treatment of insomnia and related sleep disturbances." (PMID 28769782, 2017).
intestinal-type carcinoma (1 paper, 2023). "Another study including TLR2 showed that the level of expression of these receptors was higher in patients with intestinal-type carcinoma, but these investigators did not observe correlations with intestinal-type cancer with other clinicopathological variables." (PMID 36982898, 2023).
joint diseases (1 paper, 2014). "Together these data suggest that TLR2 signaling might be a good target to limit the bone destructive potential of neutrophils in joint diseases." (PMID 24757287, 2014).
kidney (1 paper, 2023). "Numerous studies showed involvement of TLR2 in acute kidney injury." (PMID 38015955, 2023).
kidney transplant (1 paper, 2019). A surgical procedure in which one or both kidneys from a donor are implanted into a recipient. "Notably, SNPs in CASP1, CRP, IL6R, MYD88, and TLR2 have not been examined for their impact on acute rejection in kidney transplant recipients." (PMID 32153387, 2019).
lactose intolerance (1 paper, 2024). "It carried genes for the degradation of toxic metabolites, treatment of lactose intolerance, toll-like receptor 2-dependent innate immune response, heat and cold shock, bile salts tolerance, and acidic pH tolerance." (PMID 38771133, 2024).
Legionnaires' disease (1 paper, 2016). A pneumonia caused by Legionella pneumophila and other Legionella species, which is characterized by fever, cough, progressive respiratory distress, and which is often accompanied by extrapulmonary manifestations. "TLR2 rs5743708 minor genotype appeared to be associated with CAP/Legionnaires’ disease/pneumococcal disease." (PMID 27725770, 2016).
limb ischemia (1 paper, 2012). A ischemia that involves the limb. "In summary, our data suggest that mediators of innate immunity, including TLR2 and TLR4, play important roles in muscle regeneration and angiogenesis in the setting of limb ischemia." (PMID 23209800, 2012).
Löfgren's syndrome (1 paper, 2010). "Furthermore, when studying patient subgroups, a significantly lower TLR2 expression was observed in patients with Löfgren's syndrome compared to healthy subjects (p = 0.0058)." (PMID 20813038, 2010). "The reduced TLR2 expression of AMs from patients with Löfgren's syndrome may suggest a distinct innate immune response to pathogens in these patients." (PMID 20813038, 2010). "Moreover, the TLR2 down-regulation was mainly seen in patients with Löfgren's syndrome, possibly indicating that these patients respond to a particular ligand that specifically binds to TLR2." (PMID 20813038, 2010). "In addition, we studied the expression of pattern-recognition receptors TLR2 and TLR4, and found that AMs from patients, in particular those with Löfgren's syndrome, had a lower expression of TLR2." (PMID 20813038, 2010).
mastocytosis (1 paper, 2021). A clonal myeloproliferative neoplasm characterized by the proliferation and accumulation of neoplastic mast cells in one or multiple organs or organ systems. "In this study, the TLR2 p.R753Q variant was significantly more common among patients with mastocytosis compared to healthy controls and in particular those with systemic disease compared to controls." (PMID 33401724, 2021). "The presence of the TLR2 p.R753Q variant was also associated with a 2-fold increased risk for mastocytosis, and 4-fold risk for systemic disease." (PMID 33401724, 2021).
meningoencephalitis (1 paper, 2021). Inflammation of the meninges and brain, generally secondary to an infectious cause. "In addition, E. coli can cause meningoencephalitis by increasing the inflammatory response and activating the TLR2/TLR4/MyD88 and the NLRP3 inflammasome pathways." (PMID 35145923, 2021).
metastatic cancer (1 paper, 2021). A carcinoma which has spread from the original site of growth to another anatomic site. "Hence, the combination of a TLR2 agonist and GM-CSF provided greater antitumor activity in established tumor models and protected against metastatic cancer." (PMID 34599024, 2021).
metastatic tumor (1 paper, 2021). "Importantly, the cooperative antitumor effect of TLR2 agonists and GM-CSF induces distant tumor regression, suggesting that local immunity can induce systemic regression of metastatic tumors." (PMID 34599024, 2021).
Mm (1 paper, 2019). "The expression levels of cxcl11aa and cxcl11ac was significantly higher in tlr2+/− larvae than in tlr2−/− upon Mm infection." (PMID 31747871, 2019). "In agreement, the tlr2 mutant shows a significant lower expression of cxcl11aa and also of an related chemokine, cxcl11ac, during Mm infection." (PMID 31747871, 2019).
mood disorder (1 paper, 2025). A cognitive disorder a disturbance in which the person's mood is hypothesized to be the main underlying feature. "Current data propose VTX’s salubrious influences on mobility, cognition, and mood disorders, potentially attributable to its anti-inflammatory virtues, perhaps via TLR-2/NF-κB axis suppression." (PMID 40144659, 2025).
morbid obesity (1 paper, 2020). An excess of body weight, normally defined as an individual with a body mass index greater than 35 or a body weight greater than one hundred percent of ideal body weight. "Therefore, in the present project, we had the following objectives: first, we sought to study circulating levels of cytokines and soluble TLR4 in a cohort of biopsy-proven NAFLD women with morbid obesity (MO) in relation to the hepatic expression of TLRs (TLR2, TLR4, and TLR9)." (PMID 32545403, 2020).
motor neuron degeneration (1 paper, 2019). "However, the chronic systemic administration of LPS aggravates disease progression and motor neuron degeneration with the elevation of TLR2 expression, suggesting a correlation between TLR2 expression and motor neuron degeneration." (PMID 31134076, 2019).
motor neuron disease (1 paper, 2018). "TLR4/TLR2 signaling pathways may be involved in neurodegenerative disorders including motor neuron disease, cerebral hypoxia-ischemia and blood-spinal cord barrier dysfunction after ischemia/reperfusion injury, and neuropathic pain." (PMID 29803222, 2018).
Mycoplasma pneumonia (1 paper, 2025). "During infection with Mycoplasma pneumonia, Staphylococcus aureus, and Pasteurella multicoda DDX5 is degraded, preventing decay of Tlr2 and Tlr4 transcripts and promoting upregulated protein levels of TLR2 and TLR4 critical for induction of antibacterial responses." (PMID 39620586, 2025).
Mydriasis (1 paper, 2019). Abnormal dilatation of the iris. "Our results not only revealed mydriasis and overexpression of TLR2 and IL8 but correlate gB1 with important and detailed morphological changes in corneal architecture with signs of inflammation." (PMID 31487910, 2019). "The corneas exposed to gB1s show the appearance of mydriasis and high levels of TLR2 and IL-8 mRNAs transcripts were detected in the superficial layer of corneal epithelial cells." (PMID 31487910, 2019).
myelofibrosis (1 paper, 2024). A partial or complete replacement of the bone marrow stroma by fibrous tissue. "Our finding of increased TLR2 levels in PV, ET but not MF, and markedly increased ROS production in patients with myelofibrosis compared to PV or ET could likely explain this observation." (PMID 39157201, 2024).
myeloid leukemia (1 paper, 2025). A clonal proliferation of myeloid cells and their precursors in the bone marrow, peripheral blood, and spleen.
neisseria gonorrhoeae infection (1 paper, 2023). "Research has shown that activation of Nrf2 and inhibition of NF-κB resulted in a decrease in TLR2/TLR4, which could retard apoptosis and inflammation induced by neisseria gonorrhoeae infection in human endometrial epithelial cells." (PMID 37446399, 2023).
Neisseria meningitidis infection (1 paper, 2017). "Moreover, depolymerization of the MT network disrupted intracellular TLR2 and TLR4 and inhibited IL-12 production in response to Neisseria meningitidis infection." (PMID 29184543, 2017).
neurofibroma (1 paper, 2017). An intraneural or extraneural neoplasm arising from nerve tissues and neural sheaths. "In neurofibroma, Tlr2 is slightly down-regulated (0.78x) in 7-month-old neurofibroma macrophages, and Ccl2 and Ccl3, which can increase Tlr2 expression, are not significantly up-regulated." (PMID 28256556, 2017).
neurosyphilis (1 paper, 2023). Infection of the brain or spinal cord by Treponema pallidum. "Laboratory-defined neurosyphilis is associated with a common TLR1 polymorphism, while clinically and laboratory-defined neurosyphilis are both associated with common TLR2 and TLR6 polymorphisms." (PMID 37937275, 2023).
Niemann-Pick disease, type C1 (1 paper, 2024). Type C Niemann-Pick disease associated with a mutation in the gene NPC1, encoding Niemann-Pick C1 protein. "Targeting α-synuclein and TLR2 may offer therapeutic potential for modifying neuroinflammation in PD and other conditions like Niemann–Pick disease type C1 (NPC1), multiple sclerosis, AD, and stroke." (PMID 38791205, 2024).
normal tension glaucoma (1 paper, 2009). "Toll-like receptor 2 (TLR2) is a transmembrane receptor that mediates immune responses to exogenous and endogenous ligands, and interacts with heat-shock proteins, which are reportedly involved in normal tension glaucoma (NTG)." (PMID 20057905, 2009).
ocular sarcoidosis (1 paper, 2011). A leading cause of inflammatory eye disease is sarcoidosis. "In the present study, genetic variations in TLR2 did not affect ocular sarcoidosis risk." (PMID 21437199, 2011).
oesophageal cancer (1 paper, 2021). "Findings reveal that TLR2 activation in Barrett’s organoids and oesophageal cancer cells amplifies inflammation and promotes cancer development by causing the secretion of several inflammatory factors, most notably the nuclear protein, HMGB1." (PMID 33922955, 2021).
oesophagitis (1 paper, 2021). "We found that TLR2 expression, in both basal and superficial layers, was significantly correlated with both endoscopic and histological features of oesophagitis." (PMID 33686512, 2021). "In oesophagitis, the intensity and histoscore of cytoplasmic TLR2 staining increased significantly in superficial layers, but the gradient of strong staining in the basal layer to weaker staining at the surface persisted." (PMID 33686512, 2021). "In oesophagitis, TLR2 expression increased throughout the epithelium, and the superficial expression was significantly more intensive compared to normal epithelium, p <0.01." (PMID 33686512, 2021). "Similarly, in oesophagitis, nuclear TLR2 staining was significantly stronger in the superficial layer but similar in the basal layer, compared to non-inflamed epithelium." (PMID 33686512, 2021). "Could different TLR2 and TLR4 expression levels in oesophagitis be associated with disease-related changes in the oesophageal microbiome?" (PMID 33686512, 2021). "The downstream effects of TLR2 activation in oesophagitis remain speculative." (PMID 33686512, 2021). "TLR4 recognizes mostly gram-negative species; however, TLR2 does also play a role in gram-negative infections, which probably in part explains the observed increase in TLR2 expression in oesophagitis." (PMID 33686512, 2021). "TLR2, TLR4 and FXR were expressed throughout normal squamous epithelium and in oesophagitis." (PMID 33686512, 2021). "Whether alterations in TLR2 and TLR4 expression levels have any specificity for the type of oesophagitis warrants additional studies." (PMID 33686512, 2021). "Therefore, our results confirmed the role of FXR in oesophagitis and support a link between FXR and TLR2 and possibly TLR4 responses." (PMID 33686512, 2021).
oral lichen planus (1 paper, 2020). Oral lichen planus is a chronic inflammatory oral condition of unknown aetiology characterized by T-cell-mediated chronic immune response and abnormal epithelial keratinization cycle. "Smoking enhanced TLR-2 and CD34 expression in OLP which are considered as inflammatory mediators and are contributing factors in the pathogenesis of oral lichen planus." (PMID 32349717, 2020).
oral mucositis (1 paper, 2022). Inflammation of the mucous membranes of any of the structures in the mouth. "More related studies are needed to explain the relationship between TLR2 and oral mucositis." (PMID 35719331, 2022). "At present, the activation of TLR2 is generally believed to increase the expression of proinflammatory cytokines and participate in signaling pathways important in the main injury response period of oral mucositis induced by radiotherapy and chemotherapy." (PMID 35719331, 2022).
Pancytopenia (1 paper, 2021). An abnormal reduction in numbers of all blood cell types (red blood cells, white blood cells, and platelets). "We demonstrate that T cells lacking TLR2, TLR4, or IL-6 successfully induced severe pancytopenia and BMF." (PMID 33711076, 2021).
pasteurellosis (1 paper, 2020). Infections with bacteria of the genus pasteurella. "Our findings demonstrate that Pm0442 is a virulence-related gene that affects other virulence-related gene expression, and PM0442 protein directly binds to TLR2 to induce inflammatory responses of mice, which provides new guidance for the prevention and control of Pasteurellosis." (PMID 32922380, 2020).